FOSL1 (FOS like 1, AP-1 transcription factor subunit)
Diseases named in the same sentence as FOSL1 in open-access papers (continued):
Sharing a sentence is not in itself a finding about the gene and the disease.
squamous cell carcinoma (12 papers, 2007 to 2025). A carcinoma arising from squamous epithelial cells. "Similarly, miR-138 targeting of FOSL1 (which encodes Fos-like antigen 1) reduces the expression of the downstream gene, Snai2, which inhibits E-cadherin expression in squamous cell carcinoma (SCC) cells." (PMID 24057215, 2014). "In summary, the miR-138/FOSL1/Snail2 axis plays a pivotal role in the progression of squamous cell carcinoma." (PMID 38791400, 2024). "In squamous cell carcinoma, the down-regulation of FOSL1 by microRNA-138 may inhibit cell proliferation and invasion." (PMID 38791400, 2024). "It has been proposed that FOSL1 control the motility of bladder cancer cells via transcriptional up-regulation of the receptor tyrosine kinase AXL, which is also involved in squamous cell carcinoma growth through c-Jun activation." (PMID 31438567, 2019). "Fosl1 expression was detected in mutant Kras LAC cell lines but not in normal lung tissue or wild-type Kras squamous cell carcinoma cells." (PMID 28220783, 2017).
cervical carcinoma (11 papers, 2017 to 2025). A carcinoma arising from either the exocervical squamous epithelium or the endocervical glandular epithelium. "The scientists demonstrated that FOSL1 suppressed the growth of cervical cancer cells by inducing programmed cell death and altering the distribution of cells in the cell cycle." (PMID 38791400, 2024). "In order to determine if LPS can affect the FRA1 level of cervical cancer cells, we examined the changes of FOSL1 mRNA at different time points after adding LPS (50ug/ml)." (PMID 33456361, 2021). "In a single study, FOSL1 demonstrated tumor suppressor activity in cervical carcinoma." (PMID 38791400, 2024). "In cervical cancer stem-like cells (CaCxSLCs), there was an increased expression of AP-1 family members (c-Fos, c-Jun, Jun B, and Jun D) at both proteins and mRNA levels, but the FOSL1 transcript was lacking." (PMID 38791400, 2024). "In addition, we have previously shown that the FRA1 gene (FOSL1) was deleted or epigenetically silenced in ionizing radiation-induced neoplastic transformants using the CGL1 human hybrid cell line, a precancerous model of cervical cancer." (PMID 37830558, 2023).
psoriasis (11 papers, 2012 to 2026). An autoimmune condition characterized by red, well-delineated plaques with silvery scales that are usually on the extensor surfaces and scalp. "FOSL1 was identified as the TF encoding gene of psoriasis, and the enhanced FOSL1 expression was significantly correlated with high psoriasis area and severity index." (PMID 35774389, 2022). "FOSL1 can dimerize with Jun to form the Ap-1 complex, and the decreased activity of the pathway has been shown in a mouse model, with epidermal deletion of JunB/AP-1 causing psoriasis." (PMID 22957057, 2012). "FOSL1 was reported to have high level of expression in human psoriasis tissues and be able to inhibit PPARγ directly." (PMID 34445309, 2021). "Fra-1 is encoded by the FOSL1 gene and plays a role in cell proliferation and differentiation, gene expression and regulation, and the occurrence and progression of psoriasis." (PMID 36118867, 2022). "We hypothesize that the expression of IL17, STAT3, FOXP3, and RORC and FOSL1 genes in psoriatic skin is correlated with the level of PPARγ expression, and they belong to the same signaling pathway that regulates the development of psoriasis lesion." (PMID 33133175, 2020). "Increased nuclear staining intensity of FOSL1 and JUNB within keratinocytes was observed in lesional psoriasis skin irradiated with 311 nm UVB compared to 290 nm UVB and/or unirradiated lesional control skin." (PMID 33812333, 2021). "Together with induction of AP1 members FOSB, FOSL1, JUN and JUNB, and EGR signalling, our data identify regulatory pathways induced by 311 nm UVB in psoriasis that control terminal differentiation of keratinocytes." (PMID 33812333, 2021). "To further validate findings from our transcriptional analysis, we performed immunohistochemical analysis focusing on selected apoptotic and cell cycle regulatory proteins (FOSL1, GDF15, JUNB and CDKN1A) in lesional psoriasis skin (control) and 24 h after 311 nm or 290 nm irradiation." (PMID 33812333, 2021). "Moreover, the following genes were upregulated in CD3+ T cells of psoriasis patients—IL17 (105.2 ± 11.01), STAT3 (6.98 ± 1.96), RORC gene in 15.52 ± 2.18, and FOSL1 (5.79 ± 0.99)." (PMID 34445309, 2021). "Therefore, consistent with the discussion we propose that MAPKs (MAPK13 and MAPK14) and genes for AP-1 (FOSL1 and FOS) identified from sensitivity analysis of psoriasis are significant genes that might lead psoriasis towards cancer." (PMID 34267747, 2021).
bladder cancer (10 papers, 2016 to 2025). "Several of the individual genes upregulated by Gardnerella exposures are involved in epithelial to mesenchymal transition (Cxcl5, Cxcr2, Tff1) or known to be elevated during squamous metaplasia or bladder cancer (Anxa10, Fosl1, Krt6a, Mmp10)." (PMID 35782131, 2022). "In bladder cancer, HOXA10 may accelerate metastasis by regulating FOSL1 expression." (PMID 39790460, 2025).
osteosarcoma (8 papers, 2014 to 2024). A usually aggressive malignant bone-forming mesenchymal neoplasm, predominantly affecting adolescents and young adults. "Our study reveals that the osteosarcoma malignancy exhibits a dependence on CRC TFs (e.g., HOXB cluster genes and FOSL1)‐mediated oncogenic transcriptional programs." (PMID 34432948, 2021).
mesothelioma (7 papers, 2007 to 2023). A usually malignant and aggressive neoplasm of the mesothelium which is often associated with exposure to asbestos. "Among the Mesothelioma-specific hits we observed YREs in the loci of three MAPK-responsive TFs: JUN, FOSL1 and FOSB." (PMID 37400441, 2023). "In the JUN locus, we found one site upstream of its TSS (−361 Kb) highly enriched for H3K27ac and H3K4me1 histone enhancer marks and displaying mesothelioma-specific YAP occupancy, as well as binding by the AP-1 TFs FOSL1 and JUN itself." (PMID 37400441, 2023). "Additionally, the signal of H3K27ac, YAP1, JUN and FOSL1 was enriched in YREs specifically scoring in mesothelioma cells and not in common- or UM-specific hits." (PMID 37400441, 2023).
nasopharyngeal carcinoma (7 papers, 2015 to 2025). A carcinoma arising from the nasopharyngeal epithelium. "In nasopharyngeal carcinoma, the lncRNA LINC01503 can play a regulatory role in FOSL1 by influencing the SFPQ-FOSL1 axis." (PMID 40821785, 2025).
esophageal cancer (6 papers, 2009 to 2022). A primary or metastatic malignant neoplasm involving the esophagus. "Taken together, verdinexor inhibited cell proliferation and migration of esophageal cancer via XPO1/c-Myc/FOSL1 axis." (PMID 34975332, 2022). "In conclusion, verdinexor inhibits the proliferation and migration of esophageal cancer via the XPO1/c-Myc/FOSL1 axis." (PMID 34975332, 2022). "Verdinexor inhibits cell survival and migration of esophageal carcinoma via the XPO1/c-Myc/FOSL1 axis." (PMID 34975332, 2022). "Reportedly, miR-195-5p expression is down-modulated in esophageal carcinoma and miR-195-5p represses the proliferation and metastasis of cancer cells via targeting Fos-related antigen 1 (FOSL1)." (PMID 34346845, 2021). "The TCGA RNA-seq database for esophageal cancer patients showed higher expression of ATF5, BATF, and FOSL1 in cancer tissues, which is consistent with the finding of greater expression of these genes in KYSE-30 cells." (PMID 34722266, 2021). "DE VEGFA, FOSL1, MAOB, SDR16C5, RP11-58O9.2, RP11-667F14.1, and RP11-288A5.2 in hyperplastic tissues may serve as genetic targets for preventing stent restenosis in esophageal cancer." (PMID 33391336, 2020). "VEGFA, FOSL1, MAOB, SDR16C5, RP11-58O9.2, RP11-667F14.1, and RP11-288A5.2 may be served as genetic targets for preventing stent restenosis in esophageal cancer." (PMID 33391336, 2020).
pulmonary fibrosis (6 papers, 2012 to 2024). Chronic progressive interstitial lung disorder characterized by the replacement of the lung tissue by connective tissue, leading to progressive dyspnea, respiratory failure, or right heart failure. "Fra1 (FOSL1) has previously been reported as a negative regulator of AP-1 (48, –50) and its depletion enhanced bleomycin-induced lung fibrosis." (PMID 32759223, 2020).
Arthritis (5 papers, 2017 to 2025). Inflammation of a joint. "Furthermore, in an arthritis model, LPS‐induced FOSL1 was shown to directly bind to the Arginase 1 (Arg1) promoter, inhibiting its transcription and promoting macrophage polarization toward the proinflammatory M1 phenotype." (PMID 41446762, 2025).
asthma (5 papers, 2014 to 2023). "This pilot study implies a positive association between CNPY3, ERAS, FOSL1 and aspirin-intolerant asthma, suggesting that these findings would be useful for further investigations of NSAIDs mechanism." (PMID 26646719, 2015). "The network analysis revealed that transcription factor (TF) WT1, ZEB1, RERE, FOSL1, and miR-20a may be involved in the development of asthma." (PMID 35169275, 2022). "mRNA expression of FOSL1 was shown to be decreased in PBMCs of aspirin-intolerant asthma." (PMID 33791298, 2021). "Among the genes that were induced in all subjects except for patients with asthma were interferon involved genes (IL28B, IFNAR1), CCL22, and FOSL1 with respect to the upper airways, and several interferon involved genes (IRF3, IFNAR1, IFNB1, IFNGR1, IL28B) in the lower airways." (PMID 24475887, 2014).
cholangiocarcinoma (5 papers, 2022 to 2025). A carcinoma that arises from the intrahepatic biliary tree (intrahepatic cholangiocarcinoma) or from the junction, or adjacent to the junction, of the right and left hepatic ducts (hilar cholangiocarcinoma). "In cholangiocarcinoma, the TF FOSL1 modulates AURKA expression, influencing cell proliferation and tumor growth." (PMID 40746357, 2025). "HIF-1α and FOSL1 played crucial roles in driving the proliferation, invasion, and migration of cholangiocarcinoma cells within the tumor microenvironment, orchestrated by CAFs." (PMID 41048570, 2025). "HGF upregulates the phosphorylation of FOS-like 1 (FOSL1) within cholangiocarcinoma cells, promoting the expression of matrix metallopeptidase 10 (MMP10), and consequently enhancing the invasive and migratory abilities of cholangiocarcinoma cells." (PMID 41048570, 2025).
colitis (5 papers, 2014 to 2025). Inflammation of the colon. "FOSL1 belongs to the AP1 family of transcription factors; its overexpression in mice has been demonstrated to ameliorate DSS-induced colitis." (PMID 24841635, 2014).
liver cancer (5 papers, 2018 to 2023). An epithelial or non-epithelial malignant neoplasm that arises from the liver. "Finally, in invasive liver cancers, the levels of positive regulators of SERPINB2, such as TAL1 (Z-score = 3.982, p-value = 0.237), FOSL1 (Z-score = 1.483, p-value = 0.0311) and FOS (Z-score = 3.214, p-value = 0.0347), were increased." (PMID 30965654, 2019).
osteoporosis (5 papers, 2015 to 2024). A condition of reduced bone mass, with decreased cortical thickness and a decrease in the number and size of the trabeculae of cancellous bone (but normal chemical composition), resulting in increased fracture incidence. "This age-related influence was likely mediated by Fosl1(+), suggesting potential therapeutic targets for age-related bone diseases like osteoporosis." (PMID 39436962, 2024). "In fact, in the bone marrow samples of patients with osteoporosis, Cdh1 and Fosl1 were significantly upregulated while Ubap2 was significantly downregulated." (PMID 37339951, 2023). "mRNA levels of both CDH1 and FOSL1 were significantly higher in bone marrow-derived buffy coat from patients with osteoporosis than that in normal controls." (PMID 37339951, 2023). "Interestingly, the predicted transcription factors regulating TRAV140, Fosl1(+), and Lef1(+), represented promising therapeutic targets for age-related bone disorders like osteoporosis." (PMID 39436962, 2024). "Thus, the observed bone phenotype of conditional Fosl1 knockout mice is similar to low-turnover osteoporosis in humans.The inflammatory response developed by Fosl1-deficient mice after their treatment with lipopolysaccharides (LPS) is milder than in wild-type animals." (PMID 35163444, 2022). "Therefore, FOSL1, RELA and CDKN1A may also be also involved in the pathogenesis of osteoporosis." (PMID 25815782, 2015).
pancreatic ductal adenocarcinoma (5 papers, 2016 to 2026). An infiltrating adenocarcinoma that arises from the epithelial cells of the pancreas. "The context-dependent roles of Fra-1 expression are pinpointed by the inhibitory effects of FOSL1 downregulation on tumor growth, detectable in KRAS-mutated but not in KRAS-wild type PDAC (Pancreatic Ductal AdenoCarcinoma) and LUAD (LUng ADenocarcinoma) cells." (PMID 35326630, 2022).
Sepsis (5 papers, 2020 to 2025). Sepsis is defined as life-threatening organ dysfunction caused by a dysregulated host response to infection. "FOSL1 and FOSL2 have been shown to promote apoptosis in renal cells of mice with sepsis-associated nephritis and in podocytes of mice with nephrotic syndrome." (PMID 41155564, 2025). "The current study places this understanding within the context of neonatal sepsis and implicates FOSL1 not only in embryonic development, but also potentially as a mediator of impaired vascular development in the neonatal lung." (PMID 32753701, 2020). "In conclusion, we identified FOSL1 as a novel regulator of sepsis-induced deviant angiogenic signaling in mouse lung EC and human fetal HPMEC." (PMID 32753701, 2020). "Finally, validation of FOSL1 as a mediator of sepsis-induced aberrant angiogenesis in human EC enhances clinical relevance." (PMID 32753701, 2020). "The role of FOSL1 in mediating sepsis-induced pulmonary dysangiogenesis and vascular remodeling using EC-specific conditional FOSL1 knock down mice as well as the role of FOSL1 in regulating inflammatory angiogenesis in other organs are topics or future research." (PMID 32753701, 2020). "Importantly, in addition to changing the expression of Fosl1, the NTCI inhibited nuclear translocation of FOSL1 bound to cJun (AP1 protein complex) during sepsis." (PMID 37638006, 2023).
atherosclerosis (4 papers, 2022 to 2024). A disease characterized by the build-up of fatty material and calcium deposition in the arterial wall resulting in partial or complete occlusion of the arterial lumen. "FOSL1 is a potential therapeutic target to prevent diabetes-induced atherosclerosis." (PMID 36714570, 2022).
lipodystrophy (4 papers, 2013 to 2020). A congenital or acquired disorder characterized by abnormal loss or redistribution of the adipose tissue in the body. "Experiments in vivo demonstrated that Fra1 overexpression (encoding FOS like 1, AP-1 transcription factor subunit) caused severe lipodystrophy in Fra1 transgenic mice." (PMID 32089684, 2020).
metastatic tumors (4 papers, 2016 to 2023). "The highest FOSL1 expression occurs in metastatic lesions of lymph nodes where it is about 50% higher than non-metastatic tumors." (PMID 35163444, 2022). "CRC candidates, HOXB8, FOSL1, and HOXA9, were commonly and specifically associated with SEs in all chemoresistant and metastatic tumor samples." (PMID 34432948, 2021). "The metastatic tumors express more FOSL1 compared to benign tumors." (PMID 35163444, 2022).
myocardial infarction (4 papers, 2021 to 2024). Gross necrosis of the myocardium, as a result of interruption of the blood supply to the area, as in coronary thrombosis. "Although adult mice do not appear to possess a june orthologue we were able to determine that the expression of Fosl1 did not change significantly in border zone cardiomyocytes following myocardial infarction in adult mice." (PMID 38259319, 2023). "Interestingly, although the AP1 components JunB and Fosl1 are upregulated in adult zebrafish hearts after injury, the same is not true for adult mice after myocardial infarction." (PMID 38259319, 2023).
pancreatic adenocarcinoma (4 papers, 2017 to 2025). "Furthermore, FOSL1 genetic inhibition was found to be detrimental to KRAS-driven cancers such as LUAD and pancreatic adenocarcinoma." (PMID 36612054, 2022).
brain tumor (3 papers, 2013 to 2026). "Using a surrogate mouse model of MES GBM and patient-derived MES brain tumor stem cells (BTSCs), we show that FOSL1 is responsible for sustaining cell growth in vitro and in vivo, and for the maintenance of stem-like properties." (PMID 34399888, 2021). "To validate these findings at the protein level, we evaluated FOSL1 expression in glial fibrillary acidic protein (GFAP)‐positive tumor cells—used as a GBM marker—within brain tumor tissues from patients clinically categorized as TMZ resistant or TMZ sensitive." (PMID 41556041, 2026). "FOSL1 contributes to mesenchymal (MES) genes activation, cell growth, and stemness in MES brain tumor stem cells (BTSCs)." (PMID 34399888, 2021). "Using transcriptomic data of human patient-derived brain tumor stem cell lines (BTSCs), classified based on GBM-intrinsic signatures, we identify the AP-1 transcription factor FOSL1 as a key regulator of the mesenchymal (MES) subtype." (PMID 34399888, 2021).
carcinoma in situ (3 papers, 2013 to 2025). "As expected, Aldh1a3 overexpression led to increased expression of Fosl1 and Fosb and enhanced Jnk pathway activity, correlating with carcinoma in situ formation and a significant stromal reaction compared to control mice." (PMID 40781158, 2025). "Of note, FOSL1+ cells were recurrently detected in flat carcinoma in situ, suggesting that its role could be restricted to CIS-MIBC track." (PMID 31438567, 2019). "Accordingly, FOSL1 regularly resulted negative in low grade papillary NMIBC (FOSL1high = 0/20; 0%), although flat carcinoma in situ showed strong and heterogeneous expression in a fraction of cases (n = 8/11)." (PMID 31438567, 2019).
colorectal tumors (3 papers, 2014 to 2024). "Although FOSL1 expression occurs in epithelial and mesenchymal colorectal tumors, the mesenchymal cells discover more intense staining for FOSL1 than the epithelial cancer cells." (PMID 35163444, 2022). "Together, 15 of the 38 patients show a consistent increase in FOSL1, LTR10A, and LTR10F transcriptional activity in colorectal tumor cells." (PMID 39018396, 2024).
COVID-19 (3 papers, 2023 to 2024). A disease caused by infection with severe acute respiratory syndrome coronavirus 2. "Intriguingly, within these networks, certain molecular entities (RELB, DDIT3, and FOSL1) were identified as hub genes with increased expression in our patient samples during the 1-year follow-up after severe COVID-19." (PMID 39205185, 2024).
fibrosis (3 papers, 2012 to 2024). the formation of excess fibrous connective tissue in an organ or tissue in a reparative or reactive process. "Interestingly, PAX6 has previously been associated with glaucoma and FOSL1, which is associated with fibrosis, were both previously identified in an earlier study exploring the effect of αvβ3 integrin on the transcriptome of TM cells." (PMID 38394161, 2024).